NFASC (neurofascin)
Description:
Cell adhesion, ankyrin-binding protein which may be involved in neurite extension, axonal guidance, synaptogenesis, myelination and neuron-glial cell interactions.
Synonyms: KIAA0756; NRCAML; FLJ46866; NF; NEDCPMD
Tractability: Antibody: UniProt places it where antibodies can reach, with high confidence; its Gene Ontology location is reachable by antibodies, with high confidence; UniProt predicts a signal peptide or a membrane-spanning region. PROTAC: its protein half-life has been measured.
Gene: Protein-coding gene on chromosome 1 (204,828,651 to 205,022,822, forward strand). Ensembl gene ENSG00000163531.
Subcellular location: Cell membrane; Cell junction, paranodal septate junction (Isoform 8)
Pathways (Reactome):
Developmental Biology: Interaction between L1 and Ankyrins; Neurofascin interactions
Immune System: Neutrophil degranulation
Gene Ontology:
Molecular function: protein binding; cell-cell adhesion mediator activity
Biological process: axon guidance; brain development; cell-cell adhesion; myelination; peripheral nervous system development
Cellular component: focal adhesion; plasma membrane; axon; axon initial segment; ficolin-1-rich granule membrane; node of Ranvier; paranodal junction
Genetic constraint (gnomAD): Loss-of-function variants: 37 observed, 134.39 expected, observed/expected ratio (o/e) 0.28, 90% interval 0.21 to 0.36. The upper end of that interval is the gene's LOEUF score, 0.36, which puts it in group 1 of 6, group 1 being the genes least tolerant of losing a copy. Missense variants: 1,281 observed, 1,676.1 expected, observed/expected ratio (o/e) 0.76, 90% interval 0.73 to 0.8. Synonymous variants: 613 observed, 666.4 expected, observed/expected ratio (o/e) 0.92, 90% interval 0.86 to 0.98.
Homologues: Orthologues: macaque NFASC (99% identical), chimpanzee NFASC (99% identical), pig NFASC (97% identical), mouse Nfasc (96% identical), rat Nfasc (96% identical), dog NFASC (96% identical), guinea pig NFASC (96% identical), rabbit NFASC (90% identical), tropical clawed frog nfasc (70% identical), zebrafish nfasca (62% identical). Paralogues in human: NRCAM (48% identical), CHL1 (35% identical), L1CAM (34% identical), CNTN4 (23% identical), CNTN5 (22% identical), CNTN3 (21% identical), CNTN6 (21% identical), CNTN2 (21% identical), CNTN1 (20% identical), ROBO2 (17% identical), ROBO1 (16% identical), PTPRQ (16% identical), and 24 more.
Diseases named in the same sentence as NFASC in open-access papers:
NFASC is named in the same sentence as 94 diseases in open-access papers, as found by Europe PMC text mining. Sharing a sentence is not in itself a finding about the gene and the disease. The quoted sentences say what the papers report.
chronic inflammatory demyelinating polyneuropathy (15 papers, 2014 to 2025). "Accordingly, ‘contactin-associated protein’, ‘pan-neurofascin antibodies’, ‘peripheral nerve antigen’, ‘chronic inflammatory demyelinating polyneuropathy’, ‘paranodal protein’ are more recently used subject areas." (PMID 41188921, 2025). "Studies have reported that abnormal expression of NFASC is associated with chronic inflammatory demyelinating polyneuropathy and causes immune central accessory sarcoidosis." (PMID 37786892, 2022). "Anti‐neurofascin (anti‐NF) 155 antibody‐positive autoimmune nodopathy is a distinct subset of chronic inflammatory demyelinating polyradiculoneuropathy (CIDP)." (PMID 40969295, 2025). "All GBS/chronic inflammatory demyelinating polyradiculoneuropathy patients presenting with a locked-in state or similar syndrome, not otherwise explained, should be tested for nodo-paranodal pan-neurofascin antibodies." (PMID 39854764, 2025). "In chronic inflammatory demyelinating polyradiculoneuropathies, nodes of Ranvier were elongated and paranodes identified by Caspr and neurofascin immunoreactivity were dispersed whereas Caspr staining was fainter in patients with Guillain–Barré syndrome." (PMID 25348629, 2014). "In addition, chronic inflammatory demyelinating polyneuropathy (CIDP) is a known persistent variant of GBS with its own wide array of variations, including neurofascin IgG4-positive axonal nodopathy, associated with an antibody that provides an additional layer of immunoprotection." (PMID 41426823, 2025).
neuropathy (9 papers, 2018 to 2025). A disorder affecting the nervous system that manifests with pain, tingling, numbness, and/or muscle weakness. "Herein, we describe eight patients with a very severe neuropathy associated with ‘pan-neurofascin’ (panNF) IgG1-subclass antibodies." (PMID 34400540, 2021). "Furthermore, treatment of a 27-year-old patient with subacute anti-neurofascin-155 neuropathy with rituximab was associated with an improvement in clinical and neurophysiological parameters and a reduction in antibody titers and LC density." (PMID 36316419, 2022). "Rarely patients may present with very aggressive, life-threatening neuropathy associated with pan-neurofascin antibodies." (PMID 35349079, 2022). "Finally, we have reported a patient with incredibly severe but treatable neuropathy associated with autoimmunity to the common domains shared by all neurofascin isoforms." (PMID 29187518, 2018). "Neuropathy workup was integrated by anti‐neurofascin 155, anti‐panneurofascin, anti‐contactin 1 (CNTN1), and anti‐contactin associated protein 1 (CASPR1) antibodies and next‐generation sequencing for CMT, which were negative." (PMID 40685796, 2025). "The report demonstrates a case of neurofascin 186 antibody-positive neuropathy in a 46-year-old female patient." (PMID 41356854, 2025). "Several researches indicated that pan‐neurofascin antibodies identify a severe yet treatable neuropathy." (PMID 37060203, 2023). "We comprehensively examined the frequency, clinical correlates, isoform specificity, and persistence of neurofascin antibodies in patients with diverse kinds of neuropathy." (PMID 29187518, 2018). "In particular, patients with NF186 or pan‐neurofascin antibodies (against NF155, NF140, and NF186) often have a severe, GBS‐like neuropathy with cranio‐respiratory and autonomic involvement." (PMID 38813755, 2024). "Neurofascin antibodies were more common in patients with GBS/CIDP (14%, 8 of 59) compared to genetic neuropathy controls (3%, 3 of 111, p = 0.01)." (PMID 29187518, 2018). "Transient IgM responses to neurofascin occurred in some of our patients with GBS, and some of our patients with NF155 IgG4 initially presented with an acute-onset neuropathy resembling GBS." (PMID 29187518, 2018). "Patients with antibodies that cross-react with both neurofascin isoforms (NF155 and NF186) may experience a rapid onset of neuropathy." (PMID 39050350, 2024).
autoimmune neuropathy (8 papers, 2018 to 2025). An autoimmune form of peripheral neuropathy. "Recent studies suggest that pan-neurofascin antibodies are associated with severe autoimmune neuropathies, although their presence in pregnant patients has been seldom described." (PMID 41450410, 2025). "The presence of pan-neurofascin antibodies in this patient indicates a severe autoimmune neuropathy." (PMID 41450410, 2025). "The autoimmune neuropathy evaluation panel showed a marked increase in the neurofascin 186 antibody titer (623 ng/ml)." (PMID 41356854, 2025). "This case report highlights an atypical and slowly progressing presentation of autoimmune neuropathy with anti-neurofascin 186 antibodies." (PMID 41356854, 2025). "Chronic inflammatory demyelinating polyradiculoneuropathy (CIDP) with Ab against neurofascin (anti-NF Ab) is an uncommon type of autoimmune neuropathy." (PMID 32127039, 2020). "IgG1 pan-neurofascin antibodies define a very severe autoimmune neuropathy." (PMID 34400540, 2021). "Serum pan-neurofascin antibodies were strongly positive (NF155 1:1600, NF186 1:2400, IgG1), supporting an autoimmune neuropathy diagnosis." (PMID 41450410, 2025). "We do not yet know the full utility of neurofascin antibodies in diagnosing autoimmune neuropathy or in guiding treatment." (PMID 29187518, 2018).
multiple sclerosis (6 papers, 2011 to 2023). A progressive autoimmune disorder affecting the central nervous system resulting in demyelination. "Neurofascin has been identified as a prime target in the autoimmune attack of axons associated with multiple sclerosis." (PMID 21382554, 2011). "Changes in the distribution of neurofascin isoforms in the nodal domains of myelinated axons are also seen in multiple sclerosis (MS) lesions." (PMID 24465550, 2014). "Neurofascin was recently reported as a target for axopathic autoantibodies in patients with multiple sclerosis (MS), a response that will exacerbate axonal pathology and disease severity in an animal model of multiple sclerosis." (PMID 24465550, 2014). "NFASC is involved in multiple sclerosis, and ADAP1 is involved in AD." (PMID 31333395, 2019). "This is not a trivial question as multiple sclerosis is associated with a neurofascin-specific autoantibody response and preferentially affects young women." (PMID 24465550, 2014). "All multiple sclerosis patients were negative for anti-neurofascin-155 antibodies." (PMID 37091585, 2023).
Ataxia (5 papers, 2019 to 2026). Ataxia refers to impaired coordination of voluntary muscle movement. "The loss of NFASC expression caused a barrier to the formation of the initial axons, resulting in significant ataxia and decreased nerve conduction rate in rats." (PMID 35436702, 2022). "Here, we utilized exome sequencing in two siblings with progressive ataxia and muscular weakness and identified a novel homozygous splice mutation (c.3020-1G > A) in neurofascin (NFASC)." (PMID 31608123, 2019). "We therefore propose NFASC as a novel autosomal recessive disease gene associated with a phenotype that includes progressive cerebellar symptoms (vertigo, ataxia, problems with balance and motor coordination), muscle weakness, and mild cognitive impairment." (PMID 31608123, 2019). "All children had ataxia, 4 neuropathic pain (all except 1 pan-neurofascin), and 3 (2 CNTN1, and 1 pan-neurofascin) tremor." (PMID 32487720, 2020). "There are previous publications with convincing indications that loss of neurofascin in general, and NF186 in particular, causes cerebellar dysfunction and ataxia in animals." (PMID 31608123, 2019). "Antibodies directed against anti-neurofascin-155 have been linked with CIDP and tremor in 42% of cases: this tremor is usually severe, postural and mainly affects the upper limbs, but can be observed in the tongue and is usually associated with ataxia, CNS demyelination and poor response to IVIg." (PMID 39474246, 2024).
Cognitive impairment (5 papers, 2019 to 2024). Abnormal cognition is characterized by deficits in thinking, reasoning, or remembering. "Additional markers of alterations in nerve tissue repair (SPON-1 and NFASC) were elevated in those with cognitive impairment and SCG3, suggestive of brain–gut axis disturbance, was elevated in gastrointestinal symptoms." (PMID 38589621, 2024). "Muscle weakness and cognitive impairment, which were subtle findings in our patients, have not been specifically studied in neurofascin knockdown animal models." (PMID 31608123, 2019).
schizophrenia (5 papers, 2014 to 2019). A major psychotic disorder characterized by abnormalities in the perception or expression of reality. "Furthermore, in the same study, analysis of the superior temporal gyrus, a region that has been shown to be altered in schizophrenia patients, found a significant downregulation of genes encoding for NrCAM and Nav1.6 in addition to neurofascin and ankyrin G." (PMID 24913350, 2014). "The mRNA expression of NFASC is significantly downregulated in the superior temporal gyrus of persons with schizophrenia." (PMID 30341038, 2018). "For example, microarray-based gene expression analysis across all brain regions of post-mortem brains from schizophrenia patients revealed a significant decrease in the expression of ankyrin G and neurofascin when compared to control tissue." (PMID 24913350, 2014).
Guillain-Barre syndrome (4 papers, 2014 to 2026). A spectrum of rare post-infectious neuropathies that usually occur in otherwise healthy patients. "Patients with known AN (23 anti-neurofascin, 13 anti-contactin-1, and 8 anti-Caspr-1), 64 patients with seronegative (sub) acute inflammatory neuropathies, and 30 healthy controls served for validation, including quality analysis versus standard ELISA." (PMID 41906364, 2026). "Neurofascin is also a target for autoantibodies, as demonstrated by the presence of neurofascin-specific autoantibodies in patients with MS, Guillain-Barre syndrome, and chronic idiopathic demyelinating neuropathy." (PMID 24465550, 2014).
Intellectual disability (3 papers, 2018 to 2024). "Of interest, in cell-specific in silico studies, NFASC is mostly expressed in newly formed oligodendrocytes, and found to be enriched for genes associated with monogenic forms of intellectual disability." (PMID 31501903, 2019).
spinal muscular atrophy (3 papers, 2019 to 2023). A motor neuron disease that affect the muscles, and characterized by muscle weakness and atrophy resulting from progressive degeneration and irreversible loss of the anterior horn cells in the spinal cord (i.e., lower motor neurons) and the brain stem nuclei. "Another family was found within a large genetic study carrying a homozygous NFASC variant associated spinal muscular atrophy and a homozygous missense mutation leads to significant loss of NFASC protein in induced pluripotent stem cell-derived neurons from affected subjects." (PMID 31501903, 2019).
encephalitis (2 papers, 2019 to 2022). An acute inflammatory process affecting the brain parenchyma. "ELISA, enzyme‐linked immunosorbent assay; NFASC, neurofascin; NLGN2, neuroligin 2; NRXN3, neurexin 3; VE, viral encephalitis." (PMID 37786892, 2022).
nephrotic syndrome (2 papers, 2024). A collection of symptoms that include severe edema, proteinuria, and hypoalbuminemia; it is indicative of renal dysfunction. "Three of the eight (38%) patients who harbored IgG1 antibodies against NF186, NF140, and NF155 (pan‐neurofascin) had nephrotic syndrome, the histological findings of which were not reported." (PMID 38980226, 2024).
neuroblastoma (2 papers, 2009 to 2019). Neuroblastoma (NB) is the most common solid, extracranial childhood tumor. "In rat neuroblastoma cells the phosphorylated FIGQY-domain of neurofascin is bound by doublecortin." (PMID 19320973, 2009).
autoimmune disease (1 paper, 2017). A disorder resulting from loss of function or tissue destruction of an organ or multiple organs, arising from humoral or cellular immune responses of the individual to their own tissue constituents. "This could be particularly detrimental for peripheral and central autoimmune diseases that have as their molecular targets nodal antigens including NF186 resulting in a 'double-hit': disruption of nodal neurofascin and paranodal junction cytoskeletons." (PMID 28134616, 2017).
autonomic dysfunction (1 paper, 2024). "More recently, cases of severe GBS, with rapid tetraplegia, cranial nerve involvement, autonomic dysfunction and resistance to conventional treatments, have been associated with IgG1 antibodies to both neurofascin isoforms, known as anti-pan-neurofascin." (PMID 39555481, 2024).
cognitive decline (1 paper, 2023). "More studies are needed to clarify the lack of association between neurofascin 186 autoantibodies and cognitive decline." (PMID 36713900, 2023).
experimental autoimmune encephalomyelitis (1 paper, 2015). An autoimmune demyelinating disease of the central nervous system that is produced experimentally in animals by the injection of homogenized brain or spinal cord in Freund's adjuvant. "Anti-neurofascin antibody titers were more pronounced in secondary progressive MS than in relapsing-remitting MS, and adoptive transfer of neurofascin-specific antibodies caused rapid worsening of experimental autoimmune encephalomyelitis (EAE), an animal model for MS." (PMID 26511327, 2015).
lung adenocarcinoma (1 paper, 2014). A carcinoma that arises from the lung and is characterized by the presence of malignant glandular epithelial cells. "Although COL4A4, NFASC and ZNF137 show significant prognosis for overall survival and stage I, II in lung adenocarcinoma they failed to predict prognosis while correlating with the smoking history." (PMID 25401222, 2014).
lupus (1 paper, 2025). "This case highlights a unique and complex presentation of SLE in pregnancy, with concurrent lupus nephritis, AIDP with pan-neurofascin antibodies, and lupus-induced myocarditis." (PMID 41450410, 2025).
osteosarcoma (1 paper, 2023). A usually aggressive malignant bone-forming mesenchymal neoplasm, predominantly affecting adolescents and young adults. "HSPB8, RHD, AASS, and NFASC were genes we identified that have not been previously reported to be associated with osteosarcoma." (PMID 36983630, 2023). "HSPB8/RHD/AASS/NFASC has not yet been found to be associated with osteosarcoma." (PMID 36983630, 2023).
Parkinson's (1 paper, 2019). "Simultaneously, evaluation ofexpression of other 17 genes with NUCKS1 revealed that three ofthem are also have different expression in Parkinson's cases i.e.RAB7L1, NFASC and MFSD4 at P<0.01 and multiple testingcorrection (MTC) threshold 0.000345." (PMID 31719764, 2019).
polyradiculoneuropathy (1 paper, 2025). Diseases characterized by injury or dysfunction involving multiple peripheral nerves and nerve roots. "The term autoimmune nodoparanodopathy was first applied to AMAN–AMSAN but later extended to subacute/chronic forms of polyradiculoneuropathy associated with IgG4 antibodies against nodal (neurofascin [NF]-140/186) or paranodal (NF-155, contactin-1/Caspr1) axo-glial proteins." (PMID 39854764, 2025).
preeclampsia (1 paper, 2025). Preeclampsia is a hypertensive disorder of pregnancy that is characterized by new-onset hypertension with proteinuria presenting after 20 weeks of gestation, and depending on mild or severe forms may initially present with severe headache, visual disturbances, and hyperreflexia. "mRNA expression of NFASC was significantly reduced in placentas from participants who delivered an FGR infant (p = 0.03) or were diagnosed with preterm preeclampsia (p = 0.003) compared to gestation-matched controls." (PMID 40694862, 2025). "We measured NrCAM and NFASC expression in placentas complicated by FGR and/or preeclampsia." (PMID 40694862, 2025).
Respiratory insufficiency (1 paper, 2023). "Anti-pan-neurofascin (pan-NF) abs that bind to the nodal (neurofascin-186) and paranodal (neurofascin-155 (NF155)) isoform of neurofascin have been shown to induce an even more severe clinical phenotype with tetraplegia, cranial nerve involvement and respiratory insufficiency." (PMID 37388725, 2023).
Sensorimotor neuropathy (1 paper, 2015). "Antibodies against contactin-1, neurofascin and gliomedin have been reported to be present in 2–10% of patients with chronic inflammatory demyelinating polyneuropathy (CIDP) and are supposed to be associated with a typical clinical phenotype of acute onset severe sensorimotor neuropathy and tremor." (PMID 26218529, 2015). "Recent studies have described a uniform phenotype of patients with anti-neurofascin and anti-contactin-1 auto-antibodies with acute GBS-like onset of sensorimotor neuropathy following chronic course of disease and severe tremor in patients with auto-antibodies against neurofascin-155." (PMID 26218529, 2015).
Stroke (1 paper, 2015). Sudden impairment of blood flow to a part of the brain due to occlusion or rupture of an artery to the brain. "In this proteomics study, the neurogenesis-related proteins, Actn1, Gap43, Gfap, and neurofascin (Nfasc) were upregulated after the CIR-induced stroke (Neurogenesis sector)." (PMID 26492191, 2015).
tuberculous meningitis (1 paper, 2012). "We validated amphiphysin, neurofascin and ferritin light chain using immunohistochemistry which confirmed their differential expression in tuberculous meningitis." (PMID 23198679, 2012).